FUOM (fucose mutarotase)
Description:
Involved in the interconversion between alpha- and beta-L-fucoses. L-Fucose (6-deoxy-L-galactose) exists as alpha-L-fucose (29.5%) and beta-L-fucose (70.5%), the beta-form is metabolized through the salvage pathway. GDP-L-fucose formed either by the de novo or salvage pathways is transported into the endoplasmic reticulum, where it serves as a substrate for N- and O-glycosylations by fucosyltransferases. Fucosylated structures expressed on cell surfaces or secreted in biological fluids are believed to play a critical role in cell-cell adhesion and recognition processes.
Synonyms: C10orf125; FLJ26016; FucU; FucM
Tractability: PROTAC: ubiquitination databases record sites on it.
Gene: Protein-coding gene on chromosome 10 (133,353,952 to 133,358,039, reverse strand). Ensembl gene ENSG00000148803.
Pathways (Reactome):
Metabolism of proteins: GDP-fucose biosynthesis
Gene Ontology:
Molecular function: L-fucose mutarotase activity; fucose binding; racemase and epimerase activity, acting on carbohydrates and derivatives; isomerase activity; monosaccharide binding
Biological process: fucose metabolic process; GDP-L-fucose salvage; monosaccharide metabolic process
Cellular component: cytosol
Genetic constraint (gnomAD): Loss-of-function variants: 20 observed, 15.21 expected, observed/expected ratio (o/e) 1.32, 90% interval 0.92 to 1.83. The synonymous counts are far from expectation, so gnomAD's model fits this gene poorly and the ratio says little. Missense variants: 210 observed, 169.27 expected, observed/expected ratio (o/e) 1.24, 90% interval 1.11 to 1.39. Synonymous variants: 102 observed, 71.77 expected, observed/expected ratio (o/e) 1.42, 90% interval 1.21 to 1.67.
Homologues: Orthologues: macaque FUOM (95% identical), chimpanzee FUOM (86% identical), rat Fuom (79% identical), mouse Fuom (78% identical), guinea pig FUOM (75% identical), pig FUOM (66% identical), dog FUOM (64% identical), zebrafish fuom (64% identical).
Diseases named in the same sentence as FUOM in open-access papers:
FUOM is named in the same sentence as 6 diseases in open-access papers, as found by Europe PMC text mining. Sharing a sentence is not in itself a finding about the gene and the disease. The quoted sentences say what the papers report.
cervical cancer (1 paper, 2025). A primary or metastatic malignant neoplasm involving the cervix. "Specifically, we focus on FUOM, a gene identified through MR as significantly associated with cervical cancer." (PMID 40817807, 2025). "Using genetic variants as instrumental variables, we identified key genes such as FUOM, H2BC21, LAMTOR4, and PRKCQ, which demonstrated direct effects on cervical cancer susceptibility." (PMID 40817807, 2025). "scRNA‐seq revealed cell‐specific expression of key genes, including FUOM, which was elevated in cervical cancer cells." (PMID 40817807, 2025). "In migration assays, the number of migrated HeLa cells was reduced by approximately 50% following FUOM knockdown compared to the control group (p < 0.001), indicating that FUOM is critical for the migratory capacity of cervical cancer cells." (PMID 40817807, 2025). "While our experimental results provide strong support for FUOM's role in cervical cancer, further in vivo validation is necessary to confirm its effects within the complex TME." (PMID 40817807, 2025). "The observed reductions in migratory and proliferative capabilities suggest that FUOM is essential for maintaining the aggressive phenotype of cervical cancer cells." (PMID 40817807, 2025). "This study identifies FUOM as a novel driver gene in cervical cancer progression and highlights its role in tumorigenesis and immune modulation." (PMID 40817807, 2025). "Together, these experimental results validate the computational predictions, establishing FUOM as a key driver of cervical cancer progression through its roles in promoting cell proliferation, migration, and colony formation." (PMID 40817807, 2025). "Functional assays revealed that the knockdown of FUOM in HeLa cells led to significant reductions in cell proliferation (by 37%), migration (by 43%), and colony formation (by 62%), confirming its critical role in promoting cervical cancer progression." (PMID 40817807, 2025). "The correlation of FUOM and H2BC21 with immunosuppressive M2 macrophages and anti‐tumor immune cells further underscores their dual role in regulating the TME, providing actionable targets for reprogramming immune responses in cervical cancer." (PMID 40817807, 2025).
glioma (1 paper, 2026). A benign or malignant brain and spinal cord tumor that arises from glial cells (astrocytes, oligodendrocytes, ependymal cells). "Macrophage infiltration into the glioma TME was observed upon FUOM downregulation, with induced CXC motif chemokine ligand-13 (CXCL13) release in maintaining M2-like phenotype." (PMID 41957358, 2026). "FUOM was highly expressed in glioma tissues and correlated with aggressive glioma progression and unfavorable patient prognosis." (PMID 41957358, 2026). "Collectively, our work reveals that FUOM induces M2-like macrophage polarization and promotes glioma progression by mediating CXCL13 secretion." (PMID 41957358, 2026). "Then we investigated the altered proliferation, migration, and invasion capabilities of glioma cells upon regulated FUOM expression in vitro." (PMID 41957358, 2026). "Finally, blocking FUOM expression on glioma models enhanced M2-like macrophage phenotype and increased chemotactic migration both in vivo and in vitro." (PMID 41957358, 2026). "In addition, conditioned media from FUOM knockdown glioma cell lines induced M2-like macrophage chemotaxis migration." (PMID 41957358, 2026). "However, the precise role of FUOM involvement in glioma has yet to be elucidated." (PMID 41957358, 2026).
cancer (1 paper, 2025). A tumor composed of atypical neoplastic, often pleomorphic cells that invade other tissues. "For example, H2BC2's involvement in IL‐17 signaling and FUOM's association with Th17 cell differentiation suggest their potential as therapeutic targets for inflammation‐driven cancers." (PMID 40817807, 2025). "Similarly, genes like FUOM were implicated in metabolic pathways critical for sustaining tumor growth, suggesting that disrupting these pathways could limit the energy supply necessary for cancer cell proliferation." (PMID 40817807, 2025). "Functional assays demonstrated that FUOM knockdown markedly impaired cancer cell behavior." (PMID 40817807, 2025). "For example, FUOM was strongly implicated in Th17 cell differentiation, a pathway known to drive tumor‐promoting inflammation, while H2BC21 was associated with TNF and IL‐17 signaling, which are integral to immune evasion and chronic inflammation in cancer." (PMID 40817807, 2025).
tumor (1 paper, 2025). "As FUOM is implicated in both metabolic reprogramming and immune modulation, its inhibition may disrupt key processes that sustain tumor growth." (PMID 40817807, 2025). "Conversely, FUOM was highly expressed in fibroblasts, implicating it in stromal remodeling and metabolic interactions that support tumor growth." (PMID 40817807, 2025). "Moreover, the interplay between FUOM and the tumor microenvironment (TME) offers new insights into its role in shaping the immune landscape." (PMID 40817807, 2025). "Experimentally, the reduction in colony formation and proliferation following FUOM knockdown may reflect its impact on both intrinsic tumor cell properties and extrinsic factors, such as stromal remodeling or immune cell recruitment." (PMID 40817807, 2025). "Computational analyses showed that FUOM expression positively correlates with immunosuppressive M2 macrophages and negatively correlates with activated dendritic cells, underscoring its dual role in promoting immune evasion and suppressing anti‐tumor immunity." (PMID 40817807, 2025). "For instance, combining FUOM inhibition with immune checkpoint inhibitors could synergistically improve therapeutic efficacy by simultaneously targeting the tumor's metabolic dependencies and its ability to evade immune surveillance." (PMID 40817807, 2025). "Key findings include the identification of FUOM, PRKCQ, H2BC21, and LAMTOR4 as pivotal regulators of tumor progression and immune modulation, with FUOM playing a particularly prominent role in promoting cell proliferation, migration, and colony formation, as demonstrated by experimental validation." (PMID 40817807, 2025). "Genes such as FUOM and H2BC21 were positively correlated with immunosuppressive M2 macrophages and activated CD4 memory T cells, while negatively correlated with anti‐tumor immune cells such as resting CD4 memory T cells and activated dendritic cells." (PMID 40817807, 2025). "The model includes PRKCQ, FUOM, H2BC21, LAMTOR4, and HCG22, along with critical clinical factors such as age, tumor grade, and tumor stage (T and N)." (PMID 40817807, 2025). "In contrast, FUOM negatively correlated with resting CD4 memory T cells (r = −0.38, p < 0.01) and activated dendritic cells (r = −0.35, p < 0.01), indicating its potential role in impairing anti‐tumor immunity." (PMID 40817807, 2025).
FUOM also shares sentences with these, for which no sentence is quoted: infection (1 paper); Sepsis (1).